RET (ret proto-oncogene)
Diseases named in the same sentence as RET in open-access papers (continued):
Sharing a sentence is not in itself a finding about the gene and the disease.
lymph node metastasis (33 papers, 2015 to 2025). "Mutated genes associated with lymph node metastasis in the univariate analysis, including RET, ATM, PIK3CA, TERT, GGT1 and fusions, were incorporated to construct a gene signature model." (PMID 38886866, 2024). "Although not statistically significant, an association between PTC with RET fusion and lymph node metastasis seems to exist." (PMID 38734621, 2024). "Next, we analyzed the relationship between the top 10 altered genes and lymph node metastasis and found that only RET variation was associated with lymph node metastasis." (PMID 38734621, 2024). "MTC patients with RET 918 mutations are more likely to have extensive lymph node metastases in the neck and mediastinum as well as distant metastases in the liver, lungs, and bone." (PMID 38248091, 2023). "Somatic RET mutations have been demonstrated to be associated with worse prognosis, and such patients are more likely to have lymph node metastasis at initial diagnosis and have lower survival rates." (PMID 38248091, 2023). "While NCOA4::RET was associated with the tall-cell subtype, and presence of angio/lymphatic invasion and lymph node metastasis (p < 0.05)." (PMID 37188126, 2023). "The TF score was fair between wild type and RET mutation, or between primary and lymph-node metastasis groups." (PMID 36713370, 2022). "MTC in MEN2B is more aggressive than in MEN2A as MTC frequently presents in early childhood with lymph node metastasis and is caused by the germline RET codon M918T mutation in 95% of patients." (PMID 34944814, 2021). "In fact, the presence of a somatic RET mutation is associated with lymph node metastases at diagnosis, which is a bad prognostic factor for complete cure for such patients." (PMID 31717449, 2019). "The presence or higher expression of a RET fusion protein has been linked to regional invasion and lymph node metastasis." (PMID 31717449, 2019). "Patients with 918 RET mutation have a significant risk of lymph node metastases." (PMID 40340909, 2025). "NCOA4::RET rearrangements were statistically significantly associated with the tall cell subtype (p = 0.019) and angioinvasion (p = 0.001), lymphatic invasion (p = 0.003), lymph node metastasis (p= <0.001), extrathyroidal extension (p = 0.001) and extranodal extension (p = 0.013)." (PMID 37188126, 2023). "In addition to the traditional clinicopathological risk factors, specific molecular profiles (e.g., BRAF, TERT, and RET) may be used to predict the risk of extrathyroidal extension and lymph node metastases." (PMID 33392186, 2020). "All RET patients presented lymph node metastasis and 83.3% further invaded the lymph node vasculature." (PMID 40338900, 2025). "RET mutation involving exons 11 and 16, which are frequently linked to MEN 2A and MEN 2B, respectively, are strongly associated with a higher risk of lymph node metastasis, and particularly the exon 16 mutation has a very aggressive course." (PMID 40677447, 2025). "In terms of metastasis patterns, patients with ROS1 and RET fusions had a significantly higher incidence of distant lymph node metastases than patients with EGFR mutations (ROS1+ vs. EGFR+, 11.6% vs. 2.9%, p = 0.036; RET+ vs. EGFR+, 18.2% vs. 2.9%, p = 0.048)." (PMID 40751559, 2025). "Most of the patients with a RET/PTC fusion in this study had lymph node metastases and/or extrathyroidal extension." (PMID 37444504, 2023). "To reveal the potential correlation between RET fusion and TC patient lymph node metastasis, we collected the gene expression profile of the TCGA‐THCA cohort." (PMID 37081757, 2023). "In contrast, a high activity of RET (presence of CCDC6::RET rearrangement or high expression) and low activity of BRAF (absence of BRAFV600E or its low expression) were associated with lymph node metastasis." (PMID 37188126, 2023). "All six RET/PTC3-positive patients had lymph node metastases, four of these six patients had lung metastases and one patient died from disease." (PMID 31085772, 2019).
lymph node metastasis (continued). "In particular, our findings suggest that rNEN-L patients diagnosed with lymph node metastases may be more sensitive to RET inhibitors (sorafenib, vandetinib) as well as PI3K/AKT/MTOR and JAK inhibitors." (PMID 39548061, 2024). "Therefore, we enrolled age, gender, tumor diameter, and RET alteration to construct the lymph node metastasis predict nomogram." (PMID 37081757, 2023). "Her lymph node metastases (LNM) were positive only for the CCDC6/RET fusion gene." (PMID 37882481, 2023). "According to our result, patients with RET fusion tend to have more lymph node metastases." (PMID 36713542, 2022). "After restricting the sample to those with BRAF-mutant versus RET/NTRK fusion status, statistically significant associations were still found among age, AJCC N (lymph node metastasis) and M (distant metastasis, all pulmonary) categories as well as remission at 1 year (P value < .05)." (PMID 35015563, 2022). "One RET carrier had lymph node metastasis compared with 19 of 20 symptomatic patients (P = 0.0001)." (PMID 25628771, 2015). "This suggests that lymph node metastasis may be related to RET and BRAF mutation, but not RAS mutation." (PMID 38734621, 2024). "These suggest that lymph node metastasis may be related to RET and BRAF mutation, but not RAS mutation." (PMID 38734621, 2024). "The alteration frequency of RET was higher in the patients with lymph node metastasis than those without RET variation." (PMID 38734621, 2024). "High expression levels of NCOA4::RET were found, but not significant in patients with the tall-cell subtype, extrathyroidal extension, lymph node metastasis and extranodal extension." (PMID 37188126, 2023). "In contrast, patients without lymph node metastasis were found to have more frequent mutation in four genes including GATA3, FOXA1, ANKRD11, and RET (P<0.05) and more CN amplifications in two genes including PIK3C2G and CCND2 (P<0.05)." (PMID 33968723, 2021). "BRAF V600E-positive patients had more lymph node metastases reoperations due to radiorefracterity than RET/PTC-positive patients, but the difference was not statistically significant." (PMID 31085772, 2019). "A retrospective study enrolled 70 MTC patients (28 males and 42 females) without RET genetic testing with the aim of correlating NLR and PRL with lymph node metastasis and recurrence." (PMID 37373942, 2023). "The factors that showed significantly difference between patients with/without lymph node metastasis, including age, gender, ultrasound defined TI‐RADS level, tumor diameter and RET genetic alteration, were enrolled for the multivariate logistic regression analysis." (PMID 37081757, 2023).
thyroid nodule (33 papers, 2008 to 2025). A small circumscribed mass in the THYROID GLAND that can be of neoplastic growth or non-neoplastic abnormality. "For this reason, RET/PTC detection in FNAC specimens have been proposed as a diagnostic adjunctive tool in the cytological evaluation of thyroid nodules." (PMID 19578508, 2008). "Therefore, algorithmic approach of BRAF mutation analysis followed by RAS mutation and RET/PTC1 rearrangement may be of more practical help to refine FNA diagnosis of indeterminate thyroid nodules." (PMID 28417935, 2017). "The pathophysiology underlying radiation-induced thyroid nodules involves DNA damage, cellular oxidative stress, and mutations in oncogenes such as RAS and RET/PTC rearrangements." (PMID 40650298, 2025). "In one unique case of a female, different multiple mutations were found in her three thyroid nodules: CCDC6/RET + NRAS Q61R in the first nodule, CCDC6/RET + KRAS G13D in the second nodule, and NRAS Q61R + PTEN Q245* in the third nodule." (PMID 37882481, 2023). "Molecular techniques such as TsV3 enhance the management of thyroid nodules by identifying mutations highly specific for malignancy such as BRAF V600E, RET or TERT, ultimately reducing the number of diagnostic thyroidectomies required." (PMID 36612045, 2022). "Molecular tests can rule in cancer for indeterminate thyroid nodules with highly specific mutations for cancer, such as BRAF and RET/PTC." (PMID 35197932, 2022). "In benign thyroid nodules bearing RET/PTC rearrangements, there is a 4.3-fold increase in size within a timeframe of about 36 months." (PMID 34062862, 2021). "An important diagnostic impact can be achieved by testing fine needle aspiration samples, from thyroid nodules, for a panel of mutations that typically includes BRAF, RAS, RET/PTC, and PAX8/PPARg." (PMID 24955022, 2014). "The proband’s brother, who also tested positive for the RET variant, has a mildly elevated calcitonin with no thyroid nodules." (PMID 39231479, 2024). "Thus, TTE should be considered in the case of preoperative detection of an oncogenic RET fusion gene in a thyroid nodule." (PMID 37882481, 2023). "We did not measure calcitonin levels in the evaluated patients, as routine calcitonin assessment in diagnostics of thyroid nodules in children not harboring germline RET proto-oncogene mutation is not recommended." (PMID 31110490, 2019). "In this study, we performed the molecular analysis using a new simplified procedure that involves a panel of BRAF, RAS, RET and RET/PTC gene mutations in easily obtainable FNA samples, in the attempt to improve the efficacy of the FNA diagnosis of thyroid nodules and thus patient management." (PMID 28537891, 2017). "Furthermore, molecular analysis using the following markers (BRAF V600E, NRAS, HRAS, KRAS, RET/PTC, and PAX8/PPARg) to evaluate preoperative genetic mutations and rearrangements has been shown to have significant diagnostic value in thyroid nodules with indeterminate cytology." (PMID 37732121, 2023). "Considering that 88% of the PTCs harbor either a BRAF or a RAS mutation (Thyroid, 2017, Epub ahead of time), we hypothesized that detection of RET/PTC rearrangements on BRAF and RAS mutation wild-type FNA specimens of the indeterminate thyroid nodules will improve the diagnostic yield of PTC." (PMID 28417935, 2017). "Recent large prospective studies have emphasized the ability of genetic markers (BRAF, RAS, RET/PTC, and PAX8/PPARγ) and protein markers (galectin-3) to significantly improve and affect the preoperative diagnostic accuracy especially for patients who have indeterminate thyroid nodules." (PMID 23326756, 2012).
thyroid nodule (continued). "Molecular panels for indeterminate thyroid nodules range from the 7-gene panel, including BRAF, KRAS, NRAS, HRAS, RET/PTC1, RET/PTC3, and PPARG/PAX8, to 112-gene panels." (PMID 38254799, 2024). "Analysis of more than 100,000 FNA samples, including both benign and malignant thyroid nodules, identified 895 instances of NTRK, RET, ALK and BRAF fusions, representing potentially actionable kinase fusions." (PMID 36675685, 2022). "Preoperative RET/PTC1 rearrangement analysis in BRAF and RAS wild-type indeterminate thyroid nodules would permit the formulation of an unambiguous surgical plan." (PMID 28417935, 2017). "This early version is characterized by a panel including four DNA point mutations (BRAF, HRAS, NRAS, and KRAS) and three RNA translocation fusion markers (RET/PTC1, RET/PTC3, and PAX8/PPARγ) with high specificity to rule-in malignancy in indeterminate thyroid nodules." (PMID 35634500, 2022). "The presence of RET/TPC1 rearrangement in a significant proportion (38.2%) of the patients with BRAF and RAS wild-type PTCs can be used to diagnose and manage patients with BRAF and RAS wild-type indeterminate thyroid nodules." (PMID 28417935, 2017). "Preoperative RET/PTC1 rearrangement analysis in BRAF and RAS wild-type indeterminate thyroid nodules would permit the formulation of an unambiguous surgical plan, while foregoing the need for other less-specific diagnostic tests like repeat FNA and intraoperative frozen section evaluation." (PMID 28417935, 2017). "On the other hand, BRAFT1799A (V600E) is a definitive marker of malignancy, as it has never been found in benign nodules while RET/PTC has been found in nonmalignant thyroid nodules." (PMID 23326755, 2012). "Noteworthy, benign thyroid nodules exhibiting RET/PTC rearrangements do not evolve in cancer." (PMID 24267151, 2013).
papillary carcinoma (30 papers, 2000 to 2025). A malignant epithelial neoplasm characterized by a papillary growth pattern. "RET/PTC is another genetic alteration found in papillary carcinomas and was found in 1.6% of PTC in the present study." (PMID 24591770, 2014). "In other words, the expression of RET/PTC oncogene is common in papillary thyroid cancer cells (77% in concealed papillary carcinoma vs. 47% in apparent papillary carcinoma)." (PMID 23815863, 2013). "The RET/PTC family of chimeric oncogenes result from several rearrangements involving the RET gene of chromosome 10q; they are specific to papillary carcinomas and are present in up to 77% of these tumors." (PMID 20628483, 2010). "Among human tumors, RET rearrangements are restricted to the thyroid gland, where they are considered specific for papillary carcinoma." (PMID 18498667, 2008). "In the present study RET/PTC1 and RET/PTC3, the most frequent rearrangements detected in papillary carcinomas, occurred with a similar frequency: RET/PTC1 was present in five cases of PTC (10.9%) and RET/PTC3 in three cases (6.5%)." (PMID 17667921, 2007).
multiple endocrine neoplasia type 2B (29 papers, 2011 to 2026). An autosomal dominant disorder caused by specific pathogenic variants in the RET gene, characterized by an increased risk of very early onset medullary thyroid carcinoma, pheochromocytoma, and hyperparathyroidism, and mucosal neuromas. "Genetic testing revealed a SOS1 gene mutation without a RET mutation, leading to a provisional diagnosis of pure mucosal neuroma syndrome, a variant of MEN2B." (PMID 40075889, 2025). "Multiple endocrine neoplasia type 2B (MEN 2B) is a rare variant of hereditary tumor syndromes caused by germinal mutations in the proto-oncogene RET." (PMID 38312000, 2023). "This patient may represent a discrete subgroup termed pure mucosal neuroma syndrome (MNS), which presents with the characteristic appearance of MEN2B but without RET gene mutations." (PMID 37303040, 2023).
metastatic disease (28 papers, 2015 to 2026). "Lastly, systemic therapy for persistent and metastatic disease has evolved significantly over the last decade with targeted kinase therapy especially for those harboring germline or somatic RET variants." (PMID 37204852, 2023). "Systemic therapy for persistent and metastatic disease has evolved significantly with targeted kinase therapy especially for those harboring germline or somatic RET variants." (PMID 37204852, 2023). "The relatively clear genotype/phenotype relationship seen with RET mutations and the development of MEN2A is unusual in the fact that a single gene activity can drive the progression towards metastatic disease." (PMID 26065416, 2015). "RET-specific tyrosine kinase inhibitor (TKI) therapy was associated with a longer overall survival (22 months vs. undefined median survival) (P = .008) in patients with metastatic disease." (PMID 37632760, 2023). "If a RET mutation is found, either germline or somatic, in patients with aggressive metastatic disease, treatments with RET inhibitors (in the EU, the selective RET inhibitor selpercatinib) or the MKI vandetanib are available." (PMID 40540622, 2025). "Overall baseline characteristics were well-balanced between the RET high and low groups, although there were some differences in the site of metastatic disease." (PMID 39516358, 2023). "This phenomenon was in a way consistent with the clinical implications that RET-rearranged tumors were prone to be more prevalent in patients at advanced stage or with metastatic diseases." (PMID 27494860, 2016). "In this study, lymph node invasion was frequently described in patients with moderate- and high-risk RET mutations (53/127, 42%, and 48/135, 36%, respectively), but not distant metastatic disease (10/127, 8%, and 7/135, 5%, respectively)." (PMID 37835559, 2023). "Moreover, clinical utility of selpercatinib was showed also in a neoadjuvant setting, determining a RECIST response greater than 50% followed by complete surgical resection in a RET-mutated MTC patient with initially unresectable, widely metastatic disease." (PMID 35422765, 2022). "For patients with metastatic disease, the outcome largely depends on the identification of a targetable driver such as EGFR, ALK, ROS1, ERBB2, BRAF, MET and more recently KRAS, RET, NRG1 and NTRK1-2-3, as mutations or gene fusions are highly predictive of response to matched targeted therapy." (PMID 35326552, 2022). "Although the difference was not statistically significant (p = 0.23), the prevalence of patients with metastatic disease was higher in the groups of RET amplified or deleted cases while in diploid cases a higher prevalence of disease-free patients was observed." (PMID 33383911, 2020). "Indeed, if established LN metastases serve as a cancer cell reservoir for metastasis in our model, the RET mice should have developed less clinically overt metastatic tumors after CLND." (PMID 26575174, 2015). "One patient had RET mutation – in the other two cases the genetic evaluation was not available; extended germline mutations in genes associated with PHEO development and a somatic genetic test would elucidate and extend the knowledge about genotype of patients with bilateral and metastatic disease." (PMID 38318817, 2024). "Given our result that Apatinib inhibits cellular invasion and migration by fusion kinase KIF5B-RET, it may be possible of using Apatinib in tumors harboring RET gene fusions, especially those with metastatic diseases, which needs further animal studies or clinical trials to confirm." (PMID 27494860, 2016). "Finally, this study demonstrates that metastatic disease is not more frequent in MEN2 patients with high-risk RET mutations, i.e., mutations in codon C634, than in MEN2 patients with moderate-risk RET variants." (PMID 37835559, 2023).
primary hyperparathyroidism (28 papers, 2011 to 2026). "On the other hand, primary hyperparathyroidism may embrace associations with other types of adrenal tumors as seen in multiple endocrine neoplasia type 1 and 2 underlying well known pathogenic variants of MEN1 and RET." (PMID 38139166, 2023).